MMP7 (matrix metallopeptidase 7)
Diseases named in the same sentence as MMP7 in open-access papers (continued):
Sharing a sentence is not in itself a finding about the gene and the disease.
chronic lung disease (2 papers, 2007 to 2021). According to the definitions of the American and British Thoracic Societies, including pulmonary functional tests, X-rays, and CT scans for items such as fibrosis, bronchiectasis, bullae, emphysema, nodular or lymphomatous abnormalities. "Although it is clear that MMP-7 is associated with chronic lung disease, the role of MMP-7 in O3-induced airway inflammation is still unknown." (PMID 18007984, 2007). "Serum pro‐MMP‐7 activity was significantly higher in CIPF WHWTs than in dogs with chronic lung diseases (ie, CB, EBP) or healthy dogs of other breeds but not when compared with dogs with acute BP." (PMID 33274549, 2021).
cystic fibrosis (2 papers, 2017 to 2022). Autosomal recessive disorder caused by pathogenic variants in the CFTR gene (cystic fibrosis transmembrane conductance regulator), which encodes a chloride and bicarbonate channel expressed in epithelial cells, and follow the diagnosis criteria. "After injury, MMP7 expression is increased in lung epithelial cells; in human cystic fibrosis biopsy samples, MMP7 was noted to be expressed in alveolar type II cells as well as cells of the upper airway." (PMID 35204783, 2022).
dementia (2 papers, 2025). Loss of intellectual abilities interfering with an individual's social and occupational functions. "The greatest risk was conferred by the highest quartiles of GDF15, TNFR1, MMP1, MMP7, and μPAR, with participants in Q4 for each biomarker having a HR ≥ 1.6 for incident dementia relative to those in Q1." (PMID 39695064, 2025).
ductal carcinoma (2 papers, 2007 to 2016). "In particular, transcription regulators (ATF3, PIGR), genes encoding proteins with cytokine and growth factor activity (PTN, CX3CL1) and genes encoding proteins involved in ion transport and metabolism (ATP1A2, MMP7) were downregulated in ductal carcinomas when compared with normal cells." (PMID 17389037, 2007).
endothelial dysfunction (2 papers, 2021 to 2022). In vascular diseases, endothelial dysfunction is a systemic pathological state of the endothelium (the inner lining of blood vessels) and can be broadly defined as an imbalance between vasodilating and vasoconstricting substances produced by (or acting on) the endothelium. "MMP-7 is upregulated in CKD and was thus suggested as a biomarker of endothelial dysfunction in renal disorders." (PMID 34638892, 2021).
endotoxemia (2 papers, 2016 to 2020). "In the ileum of the small intestine, LPS causes the activation of MMP-7 and MMP-7 knockout mice are protected against LPS-induced leakage of the gut during endotoxemia." (PMID 33505393, 2020).
esophageal tumor (2 papers, 2021 to 2022). "Although little is known about the effect of higher MMP7 expression in astrocytomas, a correlation between MMP7 expression and tumor severity in thymic and esophageal tumors is shown." (PMID 36289737, 2022). "Consistent to this, activin was reported to enhance esophageal tumor malignancy via the upregulation of N-cadherin and MMP7 (matrix metalloproteinases 7)." (PMID 34356885, 2021).
glaucoma (2 papers, 2023 to 2025). Increased pressure in the eyeball due to obstruction of the outflow of aqueous humor. "Here we showed that MMP-7 (a matrilysin) and MMP-13 (also known as collagenase-3) are the most important MMPs in glaucoma." (PMID 36973823, 2023).
glomerular diseases (2 papers, 2020 to 2025). "This is notable because MMP‐7 has been shown to cleave nephrin ectodomains and is upregulated in several glomerular diseases." (PMID 41165237, 2025). "In glomerular diseases, MMP-7 is specifically induced in glomerular podocytes of the diseased kidney, implying its potential role in regulating podocyte injury and proteinuria." (PMID 32630493, 2020). "However, nephrin ectodomains can be shed from the podocyte cell surface by the actions of metalloproteinases such as MMP‐7, which are markedly elevated in glomerular diseases and which can be induced by NFAT signaling cascades in other cell types." (PMID 41165237, 2025).
glomerulosclerosis (2 papers, 2011 to 2021). A hardening of the kidney glomerulus caused by scarring of the blood vessels. "Consistent with marked glomerulosclerosis in UNx-Renin mice, ECM-associated gene expression changes were more pronounced in UNx-Renin mice, in which additional markers of fibrogenesis were significantly upregulated, including Col1a1, Col3a1, Col6a1, Col6a2 and Mmp7." (PMID 34494644, 2021).
H. pylori (2 papers, 2016 to 2017). "Indeed, in gastric epithelial cells, H. pylori-infection leads to increased Wnt/β-catenin reporter activity and Wnt target gene MMP7, a secreted protein that breaks down the extracellular matrix, in gastric cells." (PMID 28134850, 2017).
hyperuricemia (2 papers, 2017 to 2020). An abnormally high level of uric acid. "Interestingly, our data showed an elevated-MMP-9 level and a decreased-MMP-7 level in hyperuricemia mouse." (PMID 28445133, 2017).
injury (2 papers, 2022 to 2023). Damage inflicted on the body as the direct or indirect result of an external force, with or without disruption of structural continuity. "Recently, MMP7 has been found to correlate with BBB dysfunction following traumatic brain injury." (PMID 37977146, 2023). "MMP-7 and MMP-9 are known to cleave HS proteoglycans (including syndecan-1) and have been implicated in epithelial glycocalyx degradation in LPS- and bleomycin-induced lung injury." (PMID 34874923, 2022).
ischemia (2 papers, 2014 to 2025). A hypoperfusion of the BLOOD through an organ or tissue caused by a PATHOLOGIC CONSTRICTION or obstruction of its BLOOD VESSELS, or an absence of BLOOD CIRCULATION. "Some reports suggest that MMP-7 upregulation is protective; in an animal model study, MMP-7 knockout mice experienced higher mortality and tissue injury after ischemia, whereas exogenous MMP-7 ameliorated renal harm in MMP-7 knockout mice after ischemia/reperfusion." (PMID 40524147, 2025).
keratoconus (2 papers, 2016 to 2023). A degenerative, structural disorder of the eye, characterized by a cone-shaped protrusion of the cornea. "Partly in line with these results, increased tear levels of MMP-1, MMP-3, MMP-7, MMP-9, and MMP-13; IL-4, IL-5, IL-6, and IL-8, and TNF-α, -β were found in keratoconus." (PMID 26881061, 2016). "Elevated levels of interleukin- (IL-) 1b, IL-4, IL-5, IL-6, IL-8, and IL-17; tumor necrosis factor (TNF)-α, -β; interferon- (IFN-) γ; matrix metalloproteinase- (MMP-) 1, MMP-3, MMP-7, MMP-9, and MMP-13; Cathepsin B; and Lipocalin-1 have been found in the tears of patients with keratoconus." (PMID 26881061, 2016).
kidney inflammation (2 papers, 2020 to 2025). "However, loss of MMP7 in our model did not significantly alter any other measured outcomes including illness severity, systemic inflammation, lung inflammation, alveolar-capillary barrier permeability, lung injury, kidney dysfunction, or kidney inflammation compared to WT." (PMID 40341670, 2025). "The following potential proteases for the different CKD aetiologies were identified: ADPKD (MMP7), MCD (CTSB, CTSD, CTSE, MEP1A, MMP7, PGA3), MGN (MMP3, MMP7, MMP9, MMP13, MMP14), IgAN (MMP7), FSGS (MMP3, MMP7), vasculitis (PGA3), nephritis (MMP7, MMP9), nephrosclerosis (MMP7), and DKD (MMP9)." (PMID 32427855, 2020).
kidney injury (2 papers, 2023 to 2025). Trauma to the kidney. "We chose to focus on MMP7 in our study as it is an important regulator of kidney, systemic, and pulmonary inflammation in models of folic acid-induced kidney injury, LPS-induced systemic inflammation, and bleomycin-induced ALI." (PMID 40341670, 2025). "Kidney injury molecule-1 (KIM-1), neutrophil gelatinase-associated lipocalin (NGAL), and matrix metalloproteinase-7 (MMP-7) have been implicated in the pathogenesis of acute and long-term post-kidney injury." (PMID 37626956, 2023).
laryngeal carcinoma (2 papers, 2019 to 2022). Carcinoma that arises from the laryngeal epithelium. "FoxO1 serves a necessary function in HDAC inhibitor‐based suppression of larynx carcinoma invasion and metastasis by blocking MMP7 or by binding the ZEB2 promoter and reversing ZEB2‐induced EMT." (PMID 33772986, 2022).
medulloblastoma (2 papers, 2013 to 2021). A malignant, invasive embryonal neoplasm arising from the cerebellum. "Besides a function of MMP proteins in matrix degradation, MMP7 has been implicated in the release of bioactive molecules, such as IGF, by playing a major role in medulloblastoma pathogenesis." (PMID 23762360, 2013). "PELP1 knockdown in medulloblastoma cells results in downregulation of NF-κB, including TRAF1 and IL-8, and expression of ECM-related genes MMP7, MMP9, and MMP1465, the latter of which is upregulated by microglia in late-stage NDD development." (PMID 34772945, 2021).
mesothelioma (2 papers, 2021 to 2022). A usually malignant and aggressive neoplasm of the mesothelium which is often associated with exposure to asbestos. "In order to investigate the role of shed SDC-1 on the tube formation of endothelial cells, we silenced MMP-7 in mesothelioma cells." (PMID 33562126, 2021). "Moreover, all uterine carcinosarcoma (UCS), ESCA, mesothelioma (MESO), and KIRC cases with genetic alterations had amplification of MMP7, with frequencies around 4%, 3%, 1%, and < 1%, respectively." (PMID 35785154, 2022).
mucinous tumors (2 papers, 2012 to 2018). "Stromal expression of MMP-7 was higher also in serous compared to mucinous tumors; while the expression of MT1-MMP, MMP-7 and -9 was similar in benign and borderline tumors compared to control group." (PMID 29393911, 2018). "Similar MMP-7 profiles have been observed in mucinous tumors whatever their benign, borderline or malignant nature." (PMID 22200690, 2012).
Ovarian cyst (2 papers, 2017 to 2025). The presence of one or more cysts of the ovary. "Furthermore, significant positive correlations were noticed between the HE4 and MMP-7 (R = 0.24; p = 0.008) or TIMP-1 (R = 0.27; p = 0.002) concentrations as well as between the MMP-7 and TIMP-1 concentrations (R = 0.25; p = 0.006) in the ovarian cysts group." (PMID 28662671, 2017).
pancreatic adenocarcinoma (2 papers, 2016 to 2022). "The aim of the study was to evaluate the expression of MMP-2, MMP-7, and MMP-9 in normal ducts, tumor pancreatic adenocarcinoma cells, and peritumoral stroma in correlation with clinicohistopathological parameters." (PMID 27429508, 2016). "Therefore, the aim of our study was to evaluate the immunohistochemical expressions of MMP-2, MMP-7, and MMP-9 in the normal pancreas, pancreatic adenocarcinoma tumor cells, and stromal cells in correlation with clinicopathological features." (PMID 27429508, 2016).
pancreatic neuroendocrine tumor (2 papers, 2019 to 2022). Pancreatic endocrine tumor, also known as pancreatic neuroendocrine tumor (PNET), describes a group of endocrine tumors originating in the pancreas that are usually indolent and benign, but may have the potential to be malignant. "The expression patterns of MMP7 and TTR were also evaluated in vivo by performing an immunohistochemistry analysis of human CP samples and adjacent sections of morphologically normal pancreatic tissue obtained from patients with pancreatic neuroendocrine tumors." (PMID 35741777, 2022).
penile squamous cell carcinoma (2 papers, 2015 to 2020). "To investigate this notion, we selected four proteins associated with Wnt signalling and human penile squamous cell carcinoma: Matrix Metalloproteinase 7 (MMP7), Cyclin D1, c-Myc, and Fos-like antigen 1 (FRA1)." (PMID 32398763, 2020). "That membrane metalloproteinase targets of Wnt-ß-catenin transcription, other than MMP7, have been found to be up-regulated in PeCa support our hypothesis that Wnt signaling is likely to be active in penile squamous cell carcinoma." (PMID 25901368, 2015).
Pleural effusion (2 papers, 2020 to 2023). The presence of an excessive amount of fluid in the pleural cavity. "The diagnostic efficacy of SMRP combined with CA125, MMP-7, and MMP-9 in pleural effusion for malignant pleural effusion and BPE are better than single index, which has certain clinical values for the selection of early intervention scheme for BPE patients." (PMID 36705352, 2023). "The levels of SMRP, CA125, MMP-7, and MMP-9 in the pleural effusion were determined by enzyme linked immunosorbent assay." (PMID 36705352, 2023). "We found that in the malignant group, the levels of SMRP, CA125, MMP-7, and MMP-9 in pleural effusion were higher than those in the benign group, and all of which had a statistical significance (P = .01)." (PMID 36705352, 2023). "Expression of SMRP, CA-125, MMP-7, and MMP-9 in pleural effusion." (PMID 36705352, 2023). "We consider that SMRP, MMP-7, and CA125 may play a mutually promoting and synergistic role in the process of pleural metastasis and pleural effusion formation, but further mechanism research is needed." (PMID 36705352, 2023). "In order to determine the prognostic value of pleural effusion derived Angiopoietin-1, HGF, MMP-7, Osteopontin, TIMP-1, Galectin, Mesothelin, NRG1-b1, SDC-1 and VEGF, we divided patients in two groups depending on the established cut-off value for all analytes." (PMID 32731396, 2020).
polyp (2 papers, 2015 to 2023). A usually exophytic mass attached to the underlying tissue by a broad base or a thin stalk. "The expressions of TIMP-1, COX-2 and MMP-7 levels were significantly higher in polyp tissue compared to normal tissue (p = 0.024, p < 0.001, p = 0.009, respectively)." (PMID 29201696, 2015). "The levels of TIMP-1, COX-2 and MMP-7 in cancer tissues were higher than those of both normal tissue and polyp tissue (p = 0.009 and p = 0.001; p < 0.001 and p < 0.001; p = 0.029 and p = 0.008, respectively)." (PMID 29201696, 2015). "Expression of TIMP-1, COX-2 and MMP-7 in cancer tissues were higher than both normal tissue and polyp tissue (p = 0.009 and p = 0.001; p < 0.001 and p < 0.001; p = 0.029 and p = 0.008, respectively)." (PMID 29201696, 2015). "The mean TIMP-1, COX-2 and MMP-7 levels were significantly higher in polyp tissue compared to normal tissue (p = 0.024, p < 0.001, p = 0.009, respectively)." (PMID 29201696, 2015). "The areas under the curve for TIMP-1, COX-2 and MMP-7 were determined to be 0.647, 0.689 and 0.639, respectively and were found to be statistically significant (p = 0.024, p = 0.003 and p = 0.032, respectively) in the polyp group." (PMID 29201696, 2015).
prostate tumors (2 papers, 2016 to 2018).
psoriasis (2 papers, 2024). An autoimmune condition characterized by red, well-delineated plaques with silvery scales that are usually on the extensor surfaces and scalp. "MMP7 was independently associated with psoriasis and inflammatory responses, and could be used as a potential biomarker for psoriasis." (PMID 38526326, 2024). "Following the decrease in Livin expression, a substantial reduction was observed in the levels of inflammatory mediators, namely, MMP‐7, Cath B, CXCL 6, S100A8, S100A7, and S100A11, which have crucial functions in psoriasis." (PMID 38332513, 2024).
pulmonary hypertension (2 papers, 2021 to 2024). Increased pressure within the pulmonary circulation due to lung or heart disorder. "For example, MMP7 may participate in vascular remodelling in pulmonary hypertension." (PMID 34374413, 2021). "MMP-7 may help identify non-BA cholestatic infants who have concurrent clinically significant pulmonary hypertension." (PMID 39483898, 2024).
Renal Dysfunction (2 papers, 2024 to 2025). "Group A and D patients had elevated levels of serum creatinine and normalized urine MMP-7 values, which could be linked to their renal dysfunction." (PMID 40026998, 2025). "Furthermore, the decision curve analysis favored urine MMP-7 as a better predictor of renal dysfunction when juxtaposed with urine ACR." (PMID 40026998, 2025). "This study gauged the role of urine MMP-7 and ACR as potential indicators of renal dysfunction in diabetic individuals." (PMID 40026998, 2025).
sarcoma (2 papers, 2021 to 2022). A usually aggressive malignant neoplasm of the soft tissue or bone. "As for the disease-free survival (DFS) analysis, low expression of MMP7 was found indicating remarkably better prognosis in KIRC (P = 0.0027), LGG (P = 0.0025), sarcoma (SARC) (P = 0.044), and thymoma (THYM) with P = 0.0023." (PMID 35785154, 2022).
septic arthritis (2 papers, 2024 to 2025). "In contrast, mice deficient in MMP-7, when inoculated with S. aureus, exhibited less severe septic arthritis." (PMID 38410388, 2024). "However, they displayed higher bacterial loads in the kidneys, suggesting a pathogenic role of MMP7 in septic arthritis." (PMID 38410388, 2024). "Elevated MMP-7 contributes to S. aureus septic arthritis pathogenesis, but interestingly, it also eliminates the increased bacterial burden by enhancing bacterial clearance." (PMID 40007608, 2025).
systemic sclerosis (2 papers, 2025). A chronic disorder, possibly autoimmune, marked by excessive production of collagen which results in hardening and thickening of body tissues. "Regarding other biomarkers related to the extracellular matrix, increased MMP-7 has been a validated biomarker in systemic sclerosis ILD." (PMID 39521375, 2025). "Overall, MMP dysregulation in systemic sclerosis reflects a complex imbalance between decreased MMP-1 and MMP-13 (profibrotic suppression) and increased MMP-9, MMP-14, and MMP-7 (proinflammatory activation)." (PMID 41226358, 2025).
thymoma (2 papers, 2022 to 2023). A neoplasm arising from the epithelial cells of the thymus. "MMP-2 and MMP-7 are predominantly expressed in type B3 thymoma and thymic carcinoma, while MMP-9 is preferentially expressed in B2 thymomas." (PMID 38201593, 2023).
thyroid cancer (2 papers, 2017 to 2022). "Many MMP family members, such as MMP2, MMP7, MMP9, MMP11, and MMP13, have been implicated to be associated with the development and progression of thyroid cancer." (PMID 28709407, 2017).